BDNF (brain derived neurotrophic factor)
Diseases named in the same sentence as BDNF in open-access papers (continued):
Sharing a sentence is not in itself a finding about the gene and the disease.
Alzheimer disease (continued). "In the study of the pharmacological mechanism of G9a/GLP on early-onset Alzheimer’s disease in rat, inhibition of G9a/GLP complex could increase the levels of synaptophysin, nerve growth factor (NGF) and BDNF in brain tissues, showing a significant neuroprotective effect on rats." (PMID 34672892, 2021). "In this context a recent study reported that mimicking the beneficial effects of exercise by pharmacological induction of neurogenesis, combined with elevation of BDNF levels in the DG revert the negative effects of Alzheimer’s disease on newborn hippocampal neurons in a mouse model of the disease." (PMID 32714932, 2020). "The T allele of the BDNF C270T polymorphism was reported to be a risk factor for PTSD, schizophrenia, bulimia nervosa, and amyotrophic lateral sclerosis, but not for Alzheimer's disease." (PMID 30542302, 2018). "Indeed, the exposure of cultured brain-derived endothelial cells to inhibitors of NO production including the peptide A beta (a compound largely involved in the physiopathology of Alzheimer disease) and ADMA (an endogenous eNOS inhibitor) was reported to decrease BDNF production." (PMID 29375397, 2017). "Similarly, EGb 761 restored impaired phosphorylation of CREB and brain-derived neurotrophic factor (BDNF) expression in β-amyloid-expressing neuroblastoma cells enhancing hippocampal neurogenesis and phosphorylation of CREB in a transgenic mouse model of Alzheimer's disease (AD)." (PMID 23983787, 2013). "Brain-derived neurotrophic factor (BDNF) was significantly different (decreased) between the control and both neurodegenerative groups (PD and Alzheimer’s disease) but not between neurodegenerative groups." (PMID 32698474, 2020). "Older adults without dementia from the Alzheimer’s Disease Neuroimaging Initiative (N = 454 including 49 with T2DM and 405 without diabetes) underwent neuropsychological evaluation, magnetic resonance imaging to quantify hippocampal and WMH volumes, and blood draw to assess BDNF." (PMID 36970903, 2023). "Therefore, Mix, which increased BDNF protein expression in the CA1 region, a finding not observed in the SYG group, could be useful for treating PTSD, Alzheimer’s disease, and schizophrenia." (PMID 33097741, 2020). "The BDNF level in experimental group was significantly correlated with exercise dose based on average number of rides(r=0.50, p=.04) and related to improvements in ADAS (Alzheimer’s Disease Assessment Scale) (r=1.07, p=.01, independent of age, sex, educational level, and intervention)." (PMID 32191630, 2020).
Stroke (658 papers, 2007 to 2026). Sudden impairment of blood flow to a part of the brain due to occlusion or rupture of an artery to the brain. "In contrast, higher baseline levels of BDNF are associated with better functional independence and a reduced incidence of post-stroke depression, a common comorbidity that negatively impacts rehabilitation efficacy." (PMID 41598337, 2026). "One such biomarker is brain-derived neurotrophic factor (BDNF), a gene in which common polymorphisms have been linked to differences in post-stroke recovery." (PMID 40969674, 2025). "Our results suggest that the effect of brain-derived neurotrophic factor polymorphisms on chronic post-stroke aphasia recovery is, at best, modest and underscores the importance of individualized approaches to neurorehabilitation." (PMID 40658687, 2025). "All patients were assessed for severity and type of stroke, risk factors, and levels of plasma BDNF in the acute stroke." (PMID 41280373, 2025). "When only those whose initial naming after stroke was poor were included in analysis, we again observed that BDNF Val/Val genotype was associated with a positive odds ratio of recovering to an above average performance in naming." (PMID 40658687, 2025). "Post-stroke depression (PSD) is a prevalent neuropsychiatric disorder associated with impaired recovery in stroke survivors, potentially linked to dysregulation of brain-derived neurotrophic factor (BDNF)." (PMID 40092064, 2025). "Some key genetic markers associated with stroke are brain-derived neurotrophic factor (BDNF), apolipoprotein E (ApoE, variant ε4), angiotensin-converting enzyme (ACE), and nitric oxide synthase 3 (NOS3)." (PMID 40142325, 2025). "BDNF is known to be expressed by some Tregs, and BDNF-positive Tregs have been associated with better outcomes in stroke patients." (PMID 40940730, 2025). "This study aims to elucidate the association of BDNF levels and cholinergic markers in the plasma of patients with previously reported post-stroke walking recovery (STROKEWALK study)." (PMID 40520612, 2025). "Altogether, these pathological mechanisms lead to abnormal BDNF/TrkB-signaling which contributes to excitotoxicity, pointing to TrkB-FL and TrkB-T1 as relevant therapeutic targets for treatment of stroke and excitotoxicity-associated pathologies." (PMID 40225562, 2025). "The significant associations with lipid ratios, in particular, highlight the potential of BDNF as a biomarker for stroke risk stratification and warrant further investigation into its clinical utility." (PMID 38397057, 2024). "The delivery of BDNF has been shown to promote tissue reparative processes in various animal models of stroke and interventions that improve functional recovery are often associated with increased BDNF levels in the peri-infarct area." (PMID 38469139, 2024). "Further, brain-derived neurotrophic factor (BDNF) allele variations are indicative of stroke survivors motor function." (PMID 38802847, 2024). "Studies have shown that a low circulating BDNF level was associated with poor long-term functional outcomes after stroke, and positive outcomes have been linked to increased BDNF levels after stroke." (PMID 39469715, 2024). "In summary, BDNF plays a multifaceted role in reducing the stroke risk by influencing cell death, neurogenesis, inflammation, oxidative stress, and functional recovery." (PMID 38707431, 2024). "Low circulating BDNF levels are a well-established risk factor for stroke and impaired recovery, and stroke acutely stimulates BDNF expression in the brain." (PMID 38707431, 2024). "BDNF reduces the risk of stroke through an additional mechanism, which involves its capacity to enhance neurogenesis." (PMID 38707431, 2024). "BDNF mitigates the damage caused by inflammation and reduces the risk of stroke by modulating inflammatory responses." (PMID 38707431, 2024).
Stroke (continued). "BDNF, a nerve growth factor linked to neuronal survival, is associated with increased stroke risk in SCD patients, especially with higher transcranial Doppler (TCD) velocities." (PMID 39749215, 2024). "Polymorphisms within the serotonin transporter gene (SERT) are associated with PSD in stroke survivors, and BDNF is a significant contributor to the pathophysiological mechanisms underlying PSD." (PMID 39337894, 2024). "For example, elevated levels of certain lipids like LDL-C are known to be risk factors for IS, and BDNF has been recognized for its role in neuroprotection and neurodegeneration following stroke." (PMID 38397057, 2024). "Only two systematic reviews examined the association of BDNF concentration and polymorphism in CVDs other than stroke." (PMID 38137853, 2023). "It is well known that low levels of circulating BDNF are associated with high stroke risk and poor recovery." (PMID 36969561, 2023). "Under normal conditions, the brain’s adaptive response to stroke is to increase BDNF levels to reduce neuronal loss and promote subsequent neurogenesis." (PMID 37895349, 2023). "Overall, from our findings, a clear association emerged between low levels of BDNF, stroke, and heart failure." (PMID 38137853, 2023). "A more systematic analysis of the current evidence on the association between BDNF changes and diseases other than stroke should be performed." (PMID 38137853, 2023). "From the general findings, a key role for specific BDNF polymorphisms emerged: stroke risk was lower for the GG genotype in both homozygous and dominant models because BDNF secretion was impaired for the A allele (met-BDNF)." (PMID 38137853, 2023). "Five systematic reviews and the already cited integrative review investigated the association between BDNF genotype and stroke." (PMID 38137853, 2023). "Similar to the previous study, the current study also demonstrated that a gradually decreasing serum BDNF level after stroke onset appears to be a risk factor for poor prognosis at 3 months." (PMID 36092813, 2022). "Recent studies have shown that BDNF can also be used as a diagnostic marker for post-stroke complications and a prognostic parameter to predict the functional status of the patients with ischemic stroke." (PMID 35462697, 2022). "Recent data underline the essential role of BDNF in ischemia, suggesting its association with post-stroke mobility." (PMID 35055089, 2022). "The predictive value of serum BDNF for stroke outcome is controversial, with some studies reporting that low BDNF is associated with poor outcome poststroke, while others reported no or a weak association." (PMID 35465399, 2022). "Few studies have combined data on CST microstructure with data on BDNF polymorphisms for the prediction of motor rehabilitation after stroke." (PMID 35177977, 2022). "A previous study further found that serum BDNF levels are decreased in the acute phase of stroke, and lower circulating concentrations of BDNF protein are associated with poor long-term functional outcomes." (PMID 35572134, 2022). "In fact, BDNF has been implicated in downregulating the inflammatory response in other pathological states besides TBI/stroke." (PMID 35283994, 2022). "The BDNF Val66Met polymorphism, for instance, is associated with poor angiogenic response following stroke through upregulated anti-angiogenic mediators." (PMID 35955546, 2022). "Several studies have shown that the single-nucleotide polymorphism (SNP) val66met (G189A or rs6265) of BDNF is associated with stroke recovery." (PMID 35177977, 2022). "Supporting a role of BDNF in early stroke recovery, the val66met single nucleotide polymorphisms (SNP) of the bdnf gene is among the top polymorphisms implicated in stroke risk and prognosis." (PMID 35756121, 2022). "Shuxuening injection reverses it and promotes the recovery of post-stroke cognitive and motor deficiencies via BDNF-mediated Neurotrophin/Trk Signaling." (PMID 36158555, 2022).
Stroke (continued). "Based on the substantial impact of stroke, a systematic review and meta-analysis are essential to address the precise association of circulating BDNF in PwS in various conditions." (PMID 35287688, 2022). "A previous study reported that improvement of memory ability in rats with post-stroke rehabilitation was associated with the increase of BDNF/TrkB, as well as GAP-43 and PSD-95." (PMID 36076858, 2022). "Studies have shown that BDNF deficiency is linked to a more severe stroke pathophysiology, as BDNF plays a crucial role in developing the nervous system and promoting neuronal differentiation, cell survival, and neurogenesis." (PMID 35055089, 2022). "In parallel, those with Val/Val allele of BDNF rs6265 manifested faster and greater improvement than Met carrier on post-stroke dysphagia." (PMID 35330487, 2022). "There is evidence indicating that lower BDNF serum level is associated with increased risk of stroke or transient ischemic attack (TIA) incidence." (PMID 35462697, 2022). "Further, in the group with severe motor impairment at baseline, the number of Met alleles in the BDNF genotype was an independent predictor of stroke." (PMID 35177977, 2022). "Biomarkers of stroke risk, BDNF and PDGF-AA, were elevated in a small number of the SCA subjects, including some WITH cerebral arteriopathy and some without." (PMID 35935682, 2021). "Plasma NRG-1 was also positively correlated with elevations in both PDGF-AA and BDNF, previously reported biomarkers of high stroke risk in children with SCA." (PMID 35935682, 2021). "Studies noted that deficiency of BDNF is related to more severe stroke pathophysiology, as BDNF has a crucial role in development of the nervous system as well as promoting neuronal differentiation, cellular survival, and neurogenesis." (PMID 32944919, 2021). "For example, BDNF genotype polymorphisms negatively influenced the effect of repetitive TMS on motor recovery in stroke patients." (PMID 33804682, 2021). "In recent years, it has become clear that differences in BDNF polymorphisms affect neural plasticity, and thus the recovery of stroke patients and its mechanisms are also affected by BDNF polymorphisms." (PMID 33633556, 2021). "Intriguingly, and comparable to MI, the Val66Met BDNF polymorphism negatively impacts locomotor functions and the angiogenic response following experimentally induced stroke in rodents." (PMID 34572573, 2021). "BDNF is strongly associated with improved recovery in stroke as observed in many different studies and following systemic or intraparenchymal delivery." (PMID 32378029, 2021). "For example, the Val66Met polymorphism in the brain-derived neurotrophic factor (BDNF) gene has been linked to poor motor recovery after stroke." (PMID 34276537, 2021). "In a Framingham sub-study, low BDNF levels in healthy individuals were associated with an increased risk of future stroke/TIA." (PMID 33809965, 2021). "Another study assessed the association of the BDNF (rs6265) gene on stroke rehabilitation outcomes, revealing significant differences in functional parameters such as MBI and mRS scores between individuals under and over the age of 55 years." (PMID 34276537, 2021). "The production of endogenous BDNF in reactive astrocytes is associated with the onset of stroke in hypertensive rats, while exogenous central BDNF causes high blood pressure in hypertensive rats, leading to an increased incidence of stroke." (PMID 35194435, 2021). "Low BDNF concentrations have been noted in patients with traditional cardiovascular disease risk factors and have been associated with the increased risk of stroke/transient ischemic attack (TIA)." (PMID 33809965, 2021). "The diagnostic significance and clinical value of BDNF during the acute phase of stroke are controversial." (PMID 35194435, 2021). "In humans, decreases in BDNF levels are correlated with an increased risk of stroke, worse functional outcomes and higher mortality." (PMID 34108925, 2021).
Stroke (continued). "Typically, carriers of the Met allele of BDNF presented with poorer long-term functional outcomes after stroke." (PMID 34367374, 2021). "Some studies have drawn attention to the association between serum BDNF and functional outcomes after stroke, but there seems to be little related evidence." (PMID 33716673, 2021). "Five studies out of the seven included in this review demonstrated a significant correlation between increased risk of PSD development and low BDNF levels at some stage of stroke recovery." (PMID 34141514, 2021). "Studies have implicated Val66Met polymorphism of the brain-derived neurotrophic factor (BDNF) gene as a genetic factor influencing stroke recovery." (PMID 34367374, 2021). "For stroke, BDNF Val66Met polymorphism is associated with long-term functional outcomes, with Met allele carriers exhibiting poorer modified Rankin scale scores." (PMID 34367374, 2021). "This improvement in motor function with PDE10A inhibition is associated with elevated levels of BDNF in the striatum that has the stroke, and in enhanced angiogenesis and axonal connections in the striatum contralateral to the stroke." (PMID 32378029, 2021). "Mice with homozygous knock-in of the human BDNF Val66Met variant (BDNFMet/Met) also demonstrate reduced stroke-induced BDNF expression." (PMID 34572573, 2021). "BDNF is known to play a pivotal role in synaptic plasticity and enhanced neurogenesis in adults, and BDNF polymorphism is also known to be associated with post-stroke motor learning in adults." (PMID 33897593, 2021). "Concurrently, we tried to define the association between BDNF levels in the acute phase and stroke severity, as expressed with clinical and neuroradiological measures." (PMID 33809965, 2021). "There is limited information in the literature regarding a potential association between BDNF and type of stroke." (PMID 33343231, 2020). "The effects of the BDNF Val66Met polymorphism on neuroplasticity in motor recovery after stroke have been described in animals." (PMID 33029116, 2020). "Inflammatory insults to the brain, such as those induced by TBI and stroke, have been associated with altered BDNF levels." (PMID 33233734, 2020). "The BDNF Val66Met polymorphism was negatively associated with functional outcomes at discharge in our sample of 829 young stroke patients." (PMID 33306691, 2020). "Although the consumption of ALA by healthy individuals increases the level of BDNF, the association between the level of ALA and BDNF, especially in stroke patients, has been scantily documented so far." (PMID 33343231, 2020). "Differently from the studies of Kim and colleagues, our study, for the first time, showed the association of BDNF rs6265 polymorphism and its methylation with recovery after rehabilitation treatment in patients post-stroke." (PMID 33182716, 2020). "There is evidence indicating that lower BDNF serum level is associated with increased risk of stroke or TIA incidence." (PMID 31701356, 2020). "Although in recent years there has been an increase in clinical and preclinical studies on the role of BDNF rs6265 polymorphism in stroke, the effects on the recovery outcome post-stroke remain inconclusive." (PMID 33182716, 2020). "The local intracerebral grafting of adult mouse NPCs in the brain parenchyma is associated with elevated brain concentrations of BDNF, fibroblast growth factor, and vascular endothelial growth factor in the subacute stroke phase in mice." (PMID 32269595, 2020). "Our analysis showed that the BDNF Val66Met polymorphism was negatively associated with functional outcomes at discharge in our cadre of young stroke patients." (PMID 33306691, 2020). "It is well established that low levels of circulating BDNF are associated with a high risk of stroke and poor recovery, while BDNF expression in the brain is acutely stimulated by a stroke." (PMID 32399020, 2020).